IDH1 (isocitrate dehydrogenase (NADP(+)) 1)
Diseases named in the same sentence as IDH1 in open-access papers (continued):
Sharing a sentence is not in itself a finding about the gene and the disease.
glioma (continued). "In comparison with wild-type (WT) gliomas, human and mouse IDH1-mutant gliomas show lower inflammatory cytokine and chemokine expression, and tumor-infiltrating lymphocytes, which suggests that R-2HG facilitates the formation of the immunosuppressive TME." (PMID 41367876, 2025). "In contrast, IDH1-wildtype gliomas show elevated PD-L1 expression, which correlates with a more immunosuppressive tumor microenvironment and poorer clinical outcomes." (PMID 39906459, 2025). "In total, there were 115,673 cells from female glioma patients and 23,552 cells from female patients that were of the IDH1 mutant, the remainder being of the IDH1 wild type." (PMID 39941811, 2025). "This has successfully detected tumor-specific mutations such as IDH1/2, the TERT promoter, and histone H3 in CSF-derived cell-free DNA in gliomas with varying levels of utility." (PMID 40647477, 2025). "This demonstrated the unique genomic makeup of grade 4 IDH1/2-mutant astrocytomas, distinguishing them from glioblastoma and other grade 2 and 3 IDH1/2-mutant gliomas." (PMID 39164213, 2025). "Another study showed that the transcription factor CEBPB promoted the development of isocitrate dehydrogenase 1 wildtype (IDH1 wt) gliomas by upregulating P4HA2 protein in glioma cells at the transcriptional level." (PMID 40347062, 2025). "In our cohort, 314 patients (39.3%) had IDH1/2-mutant gliomas, while 484 (60.7%) had IDH1/2-wild-type gliomas." (PMID 41377022, 2025). "Our study demonstrated that a combination of shape- and texture-based radiomic features played a pivotal role in distinguishing IDH1-mutant from wild-type gliomas, reinforcing the growing clinical relevance of radiomics-driven machine learning models." (PMID 40299088, 2025). "Among adult-type diffuse gliomas, IDH1/2 wild-type (IDHwt) glioblastomas (GBM) express more TF than IDH1/2 mutant (IDHmut) gliomas." (PMID 40075681, 2025). "Various machine learning models were applied to predict the IDH1 genotype status in gliomas, and their performance smetrics were evaluated." (PMID 40299088, 2025). "IDH1/2-mutant gliomas and H3K27M midline tumors exemplify this mode, where metabolites such as 2-hydroxyglutarate or global H3K27me3 redistribution repress interferon pathways, chemokines (CXCL9/10), and STING signaling." (PMID 41341594, 2025). "IDH1 and IDH2 mutations frequently exist in multiple human malignancies, including acute myeloid leukemia (AML), glioma, glioblastoma, chondrosarcoma, and cholangiocarcinoma." (PMID 40863132, 2025). "In accordance with WHO CNS5 (2021) excluding IDH1-mutant glioma from glioblastoma, our cohort focuses on IDH1-wildtype." (PMID 41228352, 2025). "Prognostically, patients with IDH1/2-mutant gliomas showed superior survival than those with IDH1/2-wild-type tumors (P < 0.0001)." (PMID 41377022, 2025). "Several IDH inhibitors, approved by the FDA for other malignancies, are under investigation for IDH-mutant gliomas, including ivosidenib, olutasidenib, and safusidenib (mutant IDH1 inhibitors) and enasidenib (mutant IDH2 inhibitor)." (PMID 40657255, 2025). "Prior research has shown that the metabolic activity and epigenetic profile of gliomas, particularly in IDH1-wildtype tumors, play a significant role in regulating PD-L1 expression." (PMID 39906459, 2025). "The same EZH2 inhibition also sensitized IDH1 R132H-mutant glioma murine models to the HDAC inhibitor panobinostat." (PMID 40862786, 2025).
glioma (continued). "The alterations in IDH1 or IDH2 are dominant gain-of-function mutations, which are considered to be a prognostic marker for gliomas." (PMID 40564198, 2025). "In glioma cells, IDH mutation is a common molecular alteration, particularly the IDH1-R132H mutation." (PMID 40927709, 2025). "In a cohort of 31 glioma patients, the system achieved an area under the receiver operating characteristic curve of 0.985 for accurate IDH1 genotype differentiation." (PMID 40171868, 2025). "A recent study reported a 5-year survival rate of 68% for frontal lobe IDH1/2-mutant tumors, which was markedly higher than that (12%) observed for multilobar IDH1/2-wild-type gliomas." (PMID 41377022, 2025). "A second interesting example is isocitrate dehydrogenases (IDH1 and IDH2), enzyme-encoding genes that are frequently mutated in gliomas, acute myeloid leukemia, cholangiocarcinoma, chondrosarcoma, and thyroid carcinoma." (PMID 40330550, 2025). "Machine learning models exhibit varying trade-offs in terms of sensitivity, specificity, computational efficiency, and clinical applicability when used for IDH1 genotype classification in gliomas." (PMID 40299088, 2025). "In contrast, oligodendroglioma cases showed near-perfect concordance (97.0%) with the original diagnoses, whereas other IDH1/2-wild-type glioma cases were frequently misclassified as GBM cases (24.8%) or astrocytoma cases (23.3%) prior to molecular analysis." (PMID 41377022, 2025). "Clinically, this is crucial for treatment selection, as IDH1-mutant gliomas have a more favorable prognosis and often require different therapeutic approaches than IDH1-wildtype tumors." (PMID 40299088, 2025). "Other IDH inhibitors, such as ivosidenib, have been approved for IDH1-mutant acute myeloid leukemia but have limited data in gliomas, highlighting Vorasidenib’s unique role in this context." (PMID 40657255, 2025). "Subsequently, both H&E staining and IDH1‐R132H immunohistochemistry results verified the capability of Au‐R12P in identifying IDH1 genotypes of glioma tissues." (PMID 40171868, 2025). "For low grade gliomas, researchers are exploring mutant IDH1 targeted CAR-T cells as a potential therapy." (PMID 41583467, 2025). "IDH1-R132H mouse glioma models produce 2-HG and G-CIMP–like epigenetic remodeling, supporting a genetic-first driver of metabolic/epigenetic route." (PMID 41154717, 2025). "Similar findings have emerged from mice, where expression of IDH1(R132H) in astrocytes induces D-2HG production and promotes glioma development in sensitized backgrounds." (PMID 40236175, 2025). "IDH1/2-wild-type gliomas in elderly patients showed a marked anatomical specificity, with a high predilection for the temporal lobe and the thalamic–basal ganglia regions." (PMID 41377022, 2025). "The reduced GBO success rate experienced with lower-grade gliomas (LGGs), IDH1-mutant and recurrent tumours suggests that further optimisation and refinement of the GBO protocol will prove useful." (PMID 39799339, 2025). "SIRT7 is markedly overexpressed in higher-grade gliomas and contributes to cell proliferation, invasion, and chemoresistance through regulation of the ERK/STAT3 and IDH1-associated metabolic pathways." (PMID 40710366, 2025). "A critical trade-off in this study was between sensitivity—the ability to correctly detect IDH1-mutant gliomas—and specificity, which determines how well IDH1-wildtype gliomas are distinguished." (PMID 40299088, 2025).
glioma (continued). "IDH1(R132H) peptide vaccine (NCT02454634): The success of the IDH1(R132H) peptide vaccine in IDH-mutant gliomas provides a template for personalized neoantigen targeting." (PMID 41441679, 2025). "To further distinguish IDH1 genotypes of glioma cells, we delineated intracellular H2O2 distribution maps by measuring the I628/I928 ratio pixel by pixel." (PMID 40171868, 2025). "Mutations in IDH1 (primarily) and IDH2 have been detected in up to 70% of WHO grade II and III gliomas, and are common in secondary GBMs that can arise from these lower grade malignancies." (PMID 41450919, 2025). "A previous study revealed a strong correlation between IDH1 mutations and the nuclear localization of TET1 in glioma cells." (PMID 40520993, 2025). "Whilst direct comparisons are not possible, the order of magnitude of the methylation change (−2%) appeared similar to that found previously when we expressed mutant Idh1 in the brain in a model of IDH‐mutant glioma." (PMID 40545636, 2025). "The peak age of onset was approximately 40 years in patients with IDH1/2-mutant gliomas and approximately 50 years in patients with IDH1/2-wild-type gliomas." (PMID 41377022, 2025). "This study aims to predict the IDH1 genotype in gliomas using radiomics and machine learning (ML) methods." (PMID 40299088, 2025). "In conclusion, this study highlights RNaseH2 inhibition as a promising strategy to improve outcomes in gliomas, particularly in IDH1 wild-type cases." (PMID 41285884, 2025). "Among IDH1/2-mutant gliomas, TERTp (38.8%), CIC (24.3%), and FUBP1 (15.3%) alterations exhibited a subtype-specific distribution, with CIC/FUBP1 mutations predominant in oligodendrogliomas (62.0%/39.2%) and rare (<2%) in non-oligodendroglial subtypes." (PMID 41377022, 2025). "D-2-HG, produced by mutant IDH1/2, accumulates to millimolar levels in certain cancers, including glioma, AML, and cholangiocarcinoma." (PMID 40931345, 2025). "These metrics were used to quantify each model’s ability to distinguish between IDH1-mutant and IDH1-wildtype gliomas." (PMID 40299088, 2025). "SIRT7 regulates IDH1 transcription through its interaction with SREBP1 (Sterol Regulatory Element-binding Protein 1), influencing the production of IDH1 (Isocitrate Dehydrogenase (NADP(+)) 1) in glioma cells and their metabolic reprogramming." (PMID 40710366, 2025). "This study used machine learning models to accurately predict the IDH1 genotype in glioma classification." (PMID 40299088, 2025). "The blood flow signals in IDH1 wild-type gliomas are comparatively plentiful and significantly distorted, aligning with findings from prior MRI perfusion assessments." (PMID 40944023, 2025). "Next, we used mXO10 tLNP to deliver IDH1 R132H mRNA (mIDH1) to prepare a glioma mRNA vaccine (mXO10 tLNP@mIDH1)." (PMID 41381536, 2025). "Of 4400 gliomas were identified: 2195 glioblastomas, 1198 IDH1/2-mutant astrocytomas, 531 oligodendrogliomas, 271 other IDH1/2-wild-type gliomas, and 205 pediatric-type glioma." (PMID 39164213, 2025). "The significance of metabolic pathways to glioma pathophysiology is underscored by the isocitrate dehydrogenase-1 (IDH1) enzyme." (PMID 40507361, 2025). "The phase III “Investigating Non-enhancing Diffuse IDH-mutant Glioma Outcomes” (INDIGO) trial showed brain-penetrant IDH1/2 inhibition with vorasidenib prolonging progression-free survival in residual/recurrent IDH-mutant low-grade gliomas." (PMID 41029737, 2025).
glioma (continued). "IDH1 and IDH2 mutations are significant genetic alterations found in various tumor entities, particularly in cholangiocarcinomas, gliomas, and hematological malignancies." (PMID 40075667, 2025). "First, the in vitro experiments were conducted using a single IDH1-mut glioma cell line generated via CRISPR-Cas9, which provided a consistent genetic background and minimized variability due to inter-patient differences." (PMID 40722659, 2025). "It was proposed that IDH1 wild-type glioma's more aggressive behavior leads to the disruption of interstitial fluid and consequently the remodeling of the GS, thereby leading to the lower glymphatic function of those tumors compared to the IDH1 mutant gliomas." (PMID 40464180, 2025). "In 2021, ivosidenib received approval for IDH1-mutated cholangiocarcinoma, and in 2024, vorasidenib, a dual inhibitor of mutated IDH1/2, received FDA approval for glioma." (PMID 40004005, 2025). "Mutations associated with IDH1 and IDH2 ultimately led to the reclassification of gliomas, changing them from being glioblastomas to astrocytomas (even if high grade) and oligodendrogliomas by the World Health Organization (WHO) in 2021." (PMID 40564017, 2025). "Specific IDH1 and IDH2 mutations are characteristic of distinct subtypes, including low‐grade gliomas, secondary GBMs, chondrosarcomas, intrahepatic cholangiocarcinomas, and certain hematologic cancers." (PMID 40546878, 2025). "The safety, tolerability, and immunogenicity of the IDH1-vac vaccine in combination with the immune checkpoint inhibitor avelumab (AVE) in patients with IDH1R132H-mutant gliomas are being examined in the AMPLIFY-NEOVAC study (NCT03893903)." (PMID 40514725, 2025). "By analyzing 643 sample points from 31 glioma patients, we rapidly identify IDH1 genotypes with an area under the ROC curve of 0.985." (PMID 40171868, 2025). "In contrast, IDH1/2-wild-type gliomas predominantly originated in the temporal lobe (19.4%) and thalamic/basal ganglia (13.6%) compared to IDH1/2-mutant tumors (7.3% and 2.2%, respectively)." (PMID 41377022, 2025). "LR and Discriminant Analysis exhibited the weakest overall performance, particularly in distinguishing IDH1-mutant from wildtype gliomas." (PMID 40299088, 2025). "IDH1 shows heterogeneous distribution, reflecting its diverse metabolic functions in glioma pathophysiology." (PMID 40526188, 2025). "We identified 798 primary gliomas: 355 glioblastomas, 179 IDH1/2-mutant astrocytomas, 135 oligodendrogliomas, and 129 other IDH1/2-wild-type gliomas." (PMID 41377022, 2025). "Intraoperative identification of the isocitrate dehydrogenase type 1 (IDH1) genotype, a key molecular marker in glioma, is essential for optimizing surgical strategies and tailoring post‐surgical treatments." (PMID 40171868, 2025). "Of note, a phase I trial evaluating the combination of vorasidenib and pembrolizumab for the treatment of recurrent or progressive IDH1-mutant glioma is currently underway (NCT05484622)." (PMID 40647477, 2025). "Based on this, Huang Peng’s team developed a spray gel combining starvation therapy/chemodynamic therapy to inhibit residual IDH1 (R132H) glioma cells after surgery." (PMID 40371327, 2025). "Pediatric-type gliomas were enriched in glioblastoma (28.8%) and astrocytoma (23.4%) while other IDH1/2-wild-type gliomas were largely histologically characterized as glioblastoma (56.1%)." (PMID 39164213, 2025). "This study aimed to explore the expression of PD-L1 and IDH1 (R132H) in gliomas to evaluate their potential as prognostic biomarkers and therapeutic targets." (PMID 39906459, 2025). "We noticed that in LGG, a twisted and encircled SMI peritumoral blood flow architecture was present only in wild-type IDH1 gliomas, whereas a twisted and enlarged SMI intratumoral vascular architecture was also seen solely in wild-type IDH1 gliomas." (PMID 40944023, 2025). "In gliomas, the IDH1 R132H mutant is by far the most common, accounting for approximately 90% of all IDH mutations." (PMID 41285884, 2025).
glioma (continued). "This cohort comprised 18 cases of IDH1‐WT gliomas (13 glioblastoma, 5 astrocytoma) and 13 cases of IDH1‐MUT gliomas (7 astrocytoma, 6 oligodendrogliomas)." (PMID 40171868, 2025). "IDH1 and IDH2 (isocitrate dehydrogenase) mutations are hallmark features of lower-grade gliomas and secondary glioblastomas." (PMID 41311621, 2025). "More broadly, the unique molecular classes which emerged across IDH1/2-mutant astrocytoma with distinct survival outcomes reinforce the biological variability amongst these gliomas and the need to consider individual patient profiles." (PMID 39584448, 2025). "Compared with IDH1 wild-type, the survival of IDH1 mutant high-grade glioma patients is significantly prolonged." (PMID 40337276, 2025). "In patients with recurrent or progressing gliomas, the small-molecule inhibitor ivosidenib (AG-120), which specifically targets mutant IDH1, has shown therapeutic efficacy." (PMID 41311621, 2025). "Such mutations are found in a wide variety of human tumors and are particularly common in lower-grade gliomas, with 70%–80% of patients with grade II and III astrocytomas and oligodendrogliomas harboring IDH1 mutations." (PMID 40236175, 2025). "Collectively, these experiments underscore the ability of Au‐R12P to differentiate IDH1 genotypes of glioma cells at the cellular level." (PMID 40171868, 2025). "Multiple studies have demonstrated that tumor enhancement on magnetic resonance imaging (MRI) is more prevalent in IDH1 wild-type gliomas compared to IDH1 mutant counterparts, with the degree of enhancement correlating with a relatively poorer prognosis." (PMID 40944023, 2025). "Mutations in IDH1 or IDH2, prevalent in gliomas, AML, chondrosarcomas, and cholangiocarcinomas, confer neomorphic activity, converting α-KG to the oncometabolite D-2-hydroxyglutarate (D-2HG)." (PMID 40734168, 2025). "For example, comparative metabolomic analyses of IDH1-mutant gliomas revealed a significant increase in intracellular isocitrate levels, reflecting impaired oxidative decarboxylation of isocitrate to α-ketoglutarate and a shift in metabolic fluxes." (PMID 40931345, 2025). "IDH1 wild-type gliomas exhibit greater invasiveness compared to IDH1 mutant gliomas and represent a significant and reasonably independent prognostic indicator." (PMID 40944023, 2025). "Among these, isocitrate dehydrogenase type 1 (IDH1) stands out as a critical molecular marker for categorizing gliomas." (PMID 40171868, 2025). "This study presents a novel approach for intraoperative identification of the IDH1 genotype in glioma patients using a surface‐enhanced Raman scattering (SERS) probe to measure glutathione and hydrogen peroxide." (PMID 40171868, 2025). "Gliomas frequently exhibited concurrent aberrations in these pathways, with glioblastoma having an average of 2.8 pathways affected (median: 3), IDH1/2-mutant astrocytoma with 1.7 (median: 1), and oligodendroglioma with 1.5 (median: 1)." (PMID 39164213, 2025). "A Phase 1/2 clinical trial indicated a 12-month overall survival rate of 52.7% for IDH1 wild-type gliomas, thereby reinforcing the potential of this therapeutic strategy for treating refractory tumor types." (PMID 40698086, 2025). "APOLLO also demonstrated strong discriminative capability in resolving clinically relevant glioma methylation subtypes, specifically distinguishing between the G-CIMP-high and G-CIMP-low molecular subtypes within IDH1-mutant gliomas." (PMID 40949165, 2025). "Our study builds upon this foundation by demonstrating that gray-level texture and shape-based radiomic features are particularly effective in distinguishing IDH1-mutant from wild-type gliomas." (PMID 40299088, 2025). "This was particularly evident among low-grade gliomas, where only 32% of low-grade IDH1/2-mutant gliomas were assessed for MGMT-methylation status compared to 52% of high-grade and 82% of grade 4 IDH1/2-mutant gliomas." (PMID 39164213, 2025).